RUNX2 (RUNX family transcription factor 2)
Diseases named in the same sentence as RUNX2 in open-access papers (continued):
Sharing a sentence is not in itself a finding about the gene and the disease.
tumor (continued). "In parallel, upon RUNX2 knockdown, we have observed a predominant and strong downregulation of gene nodes known to be implicated in EOC tumorigenesis (PTGS1/COX1, FGF2, IL1A, Sapk, C/ebp, SELE, UBQLN1, PSAT1, ALDH1A1, GDF15, MTHFD2), including EOC tumor invasion/metastasis (MMP1, MMP13, Creb);." (PMID 24124450, 2013). "Several lines of evidence suggest that RUNX2 functions synergistically with a family of Smad proteins to induce osteogenesis and modulate tumor growth and metastasis.Therefore, we proceeded to determine whether Smad protein(s) have any synergistic role with RUNX2." (PMID 22966907, 2012). "Combined deletion of Runx1 and Runx2 further resulted in mammary cells becoming exquisitely sensitive to WNT-driven transformation, with expedited emergence of multiple tumours." (PMID 42092177, 2026). "IHC analysis demonstrated nuclear RUNX2 expression in both OS and EOS, observed in central tumor cores and invasive tumor areas, supporting its role in transcriptionally active tumor cells." (PMID 40862758, 2025). "This evidence underscores the molecular crosstalk between RUNX2 and HIF-1α in tumour conditions, leading to disease progression through aberrant angiogenesis, resulting in tumour vascularization and poor prognosis." (PMID 40806771, 2025). "RUNX2 emerged as a therapeutic target within this network, as its knockdown disrupted MAPK signaling and reduced tumor growth." (PMID 40781158, 2025). "Current immunohistochemical (IHC) and molecular analyses, including RUNX2, KPNA2, and SATB2 as biomarkers, support the osteogenic origin of the tumor and assist in differentiating OS from morphologically similar neoplasms." (PMID 40862758, 2025). "Similar findings have been reported in breast cancer models, in which RUNX2 knockdown activated AMPK and suppressed tumour progression." (PMID 40806771, 2025). "Subcutaneous tumor specimens were subjected to immunohistochemical (IHC) staining for Ki67, p-c-JUN, and RUNX2 proteins, along with TdT-mediated dUTP nick-end labeling (TUNEL) staining for apoptosis detection." (PMID 40410897, 2025). "Specifically, in the tumor center, TFs such as POU5F1B (Oct4) and RUNX2 are likely maintaining stem cell-like properties and driving tumor cell proliferation." (PMID 41238550, 2025). "Treatment with the histone deacetylase (HDAC) inhibitor panobinostat suppressed tumor growth both in vitro and in vivo, while also reducing expression of HEY1-NCOA2 and Runx2." (PMID 40867318, 2025). "Some TFs were specific for individual cell lines, others were shared between two cell lines, and a total of eight TFs were shared amongst all three tumor types, including TEAD1, TEAD2, TEAD3, TEAD4, GRHL2, RUNX2, AP1, and GATA6." (PMID 38912065, 2024). "Recently, we showed that MGP and RUNX2 were overexpressed in CRC tissue samples and there was a positive correlation between the two expressions in tumor mucosa." (PMID 39684309, 2024). "Overexpression of the Runt-related transcription factor 2 (RUNX2) has been reported in several cancer types, and the C-X-C motif chemokine receptor 4 (CXCR4) has an important role in tumour progression." (PMID 38474372, 2024). "WB of the harvested tumor tissues showed that circCGNL1 overexpression significantly inhibited HDAC4 phosphorylation and RUNX2 expression but promoted GAMT expression." (PMID 38297362, 2024). "In neuroblastoma, extracellular matrix stiffness controls VEGF165 secretion through the YAP/RUNX2/SRSF1 axis and regulates tumor angiogenesis." (PMID 38430423, 2024). "OstCAFs expressed numerous genes similar to OS cells (ALPL, RUNX2), with GSVA linking them to TGF_BETA_SIGNALING_PATHWAY, PATHWAYS_IN_CANCER, and WNT_SIGNALING_PATHWAY, highlighting their involvement in tumor progression." (PMID 38755647, 2024). "Overall, RUNX3 predominantly acts as a dampener of tumor stemness, distinguishing it from RUNX1 and RUNX2." (PMID 38430423, 2024).
tumor (continued). "The pathway enrichment analysis indicated upregulation of known pathways in tumor cells of SHH MB including Hedgehog, RUNX2, and interleukin-12 signaling as well as upregulation of proinflammatory cell recruitment, VEGF, and PDGF signaling in Wnt MB." (PMID 39659836, 2024). "Previous studies revealed the crucial role of the RUNX2 in the regulation of the epithelial-to-mesenchymal transition (EMT) process in many tumours, which is the first step toward tumour invasion and metastatic potential." (PMID 37759525, 2023). "As revealed by Western blot, the protein level of RUNX2 and SCD1 was prominently higher in tumor tissues than that in the adjacent normal tissues." (PMID 36200301, 2023). "Macrophage infiltration was recorded in 22 tumor types for RUNX1, in 25 types for RUNX2, and in 18 types for RUNX3." (PMID 36321611, 2023). "To investigate MSN’s tumor-promoting effect on CRC via RUNX2, we silenced RUNX2 expression in MSN-overexpressing cells by transfecting shRNA against RUNX2 (RUNX2-shRNA)." (PMID 37446127, 2023). "The RUNX family of transcription factors, including RUNX1, RUNX2, and RUNX3, are key regulators of development and can function as either tumor suppressors or oncogenes in cancer." (PMID 37190015, 2023). "A significant positive correlation was noted between RUNXs expression and B cell infiltration in several tumor types; specifically, in 17 types for RUNX1, in 18 types for RUNX2, and in 21 types for RUNX3." (PMID 36321611, 2023). "Several top pathways identified using only tumor specific sex-DMPs in SHH were also found in the top SHH pathways using all sex-DMPs, including regulation of RUNX2 expression and activity." (PMID 37035203, 2023). "The family of Runt-related (RUNX) genes (RUNX1, RUNX2, and RUNX3) is crucial for the different tumour types’ development and progression." (PMID 37759525, 2023). "We further explored the relationship between the different RUNXs expression and the abundance of tumor-infiltrating lymphocytes (TILs) through TISIDB analysis and found that RUNX1, RUNX2, and RUNX3 were positively correlated with TILs." (PMID 36321611, 2023). "If left unchecked, RUNX2 and RANKL signaling promotes osteoclasts to engage in a vicious cycle of bone matrix resorption and growth factor release that favors tumor growth and survival." (PMID 38435029, 2023). "RUNX2 overexpression increases matrix metalloproteinase (MMP) expression and the invasion activity of the tumor, leading to PCa progression and metastasis." (PMID 38435029, 2023). "CD8+ T cell infiltration was recorded in 21 tumor types for RUNX1, in 18 types for RUNX2, and in 21 types for RUNX3." (PMID 36321611, 2023). "Three RUNX transcription factors, RUNX1, RUNX2, and RUNX3, along with their cofactor CBFβ, exert tumor-related functions in a context-dependent manner." (PMID 37190031, 2023). "RUNX2 knockdown also led to the decreased levels of RUNX2, MMP13 and MGAT5 in mice tumor tissues when assessed by western blotting or IHC assay." (PMID 37256183, 2023). "As illustrated in the heat maps, a negatively significant correlation was noted between RUNXs expression and the tumor purity in several tumor types; specifically in 19 tumor types for RUNX1, in 21 types for RUNX2, and in 23 types for RUNX3." (PMID 36321611, 2023). "KI-67, RUNX2 and SATB2 expression differed depending on the benign or malignant course of the tumor under denosumab therapy." (PMID 37686526, 2023). "Treatment with the HDAC inhibitor panobinostat suppressed tumor growth both in vitro and in vivo, abrogating expression of genes downstream of HEY1-NCOA2 and Runx2." (PMID 37212282, 2023). "Taken together, our study further correlates ALPL and RUNX2 signaling with the molecular signaling of RANKL and MMP, a modulation that affects the tumor cell invasiveness and phenotypic plasticity." (PMID 38435029, 2023).
tumor (continued). "Through the HPA database, we found that three genes (ABCC9, AHNAK, and DIP2C) had low expression in patients with tumours, whereas eight genes (PLOD1, SLC3A2, RUNX2, RAD9A, CHMP4C, DARS2, CLIC3, and POU5F1) were highly expressed." (PMID 36685927, 2022). "Experiments using tumor samples derived from the tumor xenograft mouse models demonstrated that the expression of CBFB, OPN, Runx2, and CXCR4 proteins was significantly suppressed in CBFB-knockdown mice, compared with the control mice." (PMID 35903297, 2022). "To elucidate the mechanism of the anti-tumor action of Hsp90ab1 and MSN, we evaluated their downstream protumorigenic genes such as TGFβ, Runx2, Snail, and MMP9, as well as PDL1 24 that inhibits immune responses and KDM3A 25 that regulates histone methylation." (PMID 34976221, 2022). "By inhibiting c-MYC and RUNX2 expression, JQ1 decreased OB differentiation and tumour progression, suppressing c-MYC and RUNX2 expression." (PMID 35681577, 2022). "In this study, CBFB knockdown decreased tumor burden, bone metastasis, and markers of bone metastasis, including CXCR4, Snail, CD44, OPN, Runx2, and IL-6." (PMID 35903297, 2022). "In clear cell RCC, SNHG12, as a competitive endogenous RNA, competes with miR-30a-5p to bind to downstream oncogenes RUNX2, IGF-1R and WNT2 to promote tumor cell invasiveness." (PMID 35597996, 2022). "We also investigated at the pan-cancer and inter-tumor heterogeneity of RUNX gene family expression, and found that RUNX1 and RUNX3 were highly expressed at the pan-cancer level, whereas RUNX2 was modestly expressed." (PMID 35522574, 2022). "Activation of AKT in PC BM increased expression of RUNX2 and RUNX2-dependent genes (e.g., MMP9) in tumor cells, facilitating invasion." (PMID 35159026, 2022). "Silencing CD44 and FN1 in EO771 cells and MDA-MB-231 cells downregulated MTT-based viability as well as the expression of Lrp5, MMP9, Runx2, and Snail in EO771 cells, whereas their silencing significantly suppressed MSN-induced tumor inhibition." (PMID 34976221, 2022). "While three genes (AHNAK, ABCC9, and DIP2C) were highly expressed in normal tissues, eight genes (CHMP4C, CLIC3, DARS2, PLOD1, POU5F1, RAD9A, RUNX2, SLC3A2) were highly expressed in tumour tissues." (PMID 36685927, 2022). "In response to the loading-driven elevation of dopamine, we evaluated the expression of Lrp5 and downstream effector genes in tumor cells, including tumor-promoting cytokines and oncogenic genes such as Src, Snail, MMP9, Runx2, and TGFβ." (PMID 34031366, 2021). "The interaction of RUNX2 and LAMC2 with the PI3K/AKT and MAPK signaling pathways can act as a driving force in controlling tumor progression." (PMID 34606473, 2021). "In a second validation study, we explored the expression of RUNX2 and LAMC2 in different clinical stage, sex, age, tumor subtype and personal tumor status groups." (PMID 34606473, 2021). "The next step was the determination of the potential downstream effector, which links loading-driven regulation of the dopamine-Lrp5 axis to tumor-promoting genes such as Snail, MMP9, and Runx2." (PMID 34031366, 2021). "Hsp90ab1 reduced the scratch-based migration and downregulated tumor-promoting genes Lrp5, MMP9, Runx2 and Snail in 4T1.2 cells." (PMID 33859739, 2021). "In contrast to Lrp5-overexpressing osteocytes, Lrp5-overexpressing astrocyte-derived CM promoted the viability and migration of EO771 tumor cells, and the level of MMP9, Runx2, and Snail in EO771 cells were upregulated." (PMID 33802279, 2021). "The tumor-promoting genes (Lrp5, MMP9, Runx2 and Snail) in EO771 cells were decreased by treating with Snail-overexpressing MSC CMs and the effect was reversed by silencing Snail." (PMID 33859739, 2021).
tumor (continued). "miR-223-3p repression led to increased expression of tumor supportive cytokines VEGF and IL6 and inhibition of the osteogenic potential of MM-MSCs, as indicated by reduced expression of RUNX2 and OPN, as well as reduced calcification and ALPL activity." (PMID 33673480, 2021). "In examining the dissected tumor tissues, both dipyridamole and GW4869 decreased protein contents in cyclin D1, β-catenin, YAP1, Runx2, phosphorylated Smad2/3, HMGB1, RAGE, and CD42b, except the TLR4." (PMID 33669632, 2021). "Next, we explored RUNX2 expression in NPC tissue; our IHC data showed that RUNX2 expression levels were significantly increased in tumor tissues, which were further confirmed using the TCGA database." (PMID 34093832, 2021). "This, alongside RUNX2 and RUNX1 cooperation in tumour cells and RUNX1 recruitment to the E-cad promoter, raises a possibility of similar recruitment of RUNX2, and therefore Rb, to the E-cad promoter." (PMID 34262912, 2021). "The co-culturing of tumor spheroids with Lrp5-overexpressing osteocyte spheroids shrank tumor spheroids, and their CM downregulated MMP9, Runx2, TGFβ, and Snail." (PMID 33450808, 2021). "The expression of FXR, Runt-related transcription factor 2 (RUNX2) and bone proteins were evaluated on two tumor cell lines (MCF-7 and MDA-MB-231) by immunohistochemistry, immunofluorescence and western blotting and quantified." (PMID 32650752, 2020). "Further mechanical studies demonstrated that SNHG4 functioned as a ceRNA to sponge miR-204-5p, then upregulate RUNX2, to promote RCC tumor progression." (PMID 33088220, 2020). "Some studies suggest that RUNX2 has the ability to transactivate its downstream target genes, such as MMP9, MMP13, VEGF, survivin, and IL-8, which are involved in tumor progression, invasion, and metastasis." (PMID 33313404, 2020). "Other candidates such as EGR1, RUNX2, STAT1, TRAP2, IRF1 and USF1 have been experimentally validated as drug targets, metastasis promoter or tumor growth enhancers, see19–24." (PMID 31857653, 2019). "By transient restoration of Runx2 in miR-196a-downregulated HCC in vivo, aggressive tumor phenotypes can be restored." (PMID 31614906, 2019). "In summary, our study not only reveals a novel positive feedback loop among RUNX2, PTHLH, and calcium but also shows RUNX2/PTHLH axis promotes HNSCC tumor growth." (PMID 28120940, 2017). "Using ChIP-qPCR assay, we demonstrated that RUNX2 binds directly to PTHLH promoter and thereby stimulates PTHLH expression which appears to be important for promoting tumor growth in Ca9-22 cells." (PMID 28120940, 2017). "OPN, Runx2, and MMP-7 showed increased expression in the advanced stage of liver metastasis but subsequently showed reduced expression after the isolated tumor cells had been further cultured in vitro." (PMID 28770169, 2017). "Overexpression of activated RUNX2 and hyperactivation of AKT represent two characteristics of pro-migratory and pro-invasive tumor cells." (PMID 26204939, 2015). "The effects on tumorsphere formation are consistent with known roles for RUNX2 and TAZ in tumor-initiating functions." (PMID 26320173, 2015). "High copy RIS mapping to Runx2 or Runx3 were almost ubiquitous in, but exclusive to, CD2-MYC tumours (P = 0.0001, Fisher's Exact Test)." (PMID 24586197, 2014). "These genes (RUNX1, RUNX2 and RUNX3) exhibit context-dependent oncogenic and tumour-suppressive properties through pertinent effects on cell growth and viability." (PMID 24626992, 2014). "A recent study identified RUNX2 as a potent prognostic factor in non-small cell lung cancer (NSCLC) patients, as RUNX2 expression was significantly correlated with NSCLC tumor progression and metastatic capability." (PMID 24124450, 2013).
tumor (continued). "Repositioning of the centromere was also detected, and reordering of many of the genes remaining on chromosome 4 in the tumour (e.g.GNL1 and RUNX2)." (PMID 22359511, 2012). "To investigate whether the RUNX2 effect on metabolism represents a cross-sectional mechanism in other cancers, we used MDA-MB231 and Hs578T as BC metastasis and primary tumor models." (PMID 41174748, 2025). "RUNX2 plays a central role in the epithelial–mesenchymal transition (EMT), a critical process facilitating cancer cell migration and invasion, which ultimately promotes tumor progression." (PMID 40332124, 2025). "A highly expressed RUNX2 may activate, at a transcriptional level, tumor-promoting genes such as OPN, whereas RUNX2 depletion can hamper lung metastasis in vivo." (PMID 41511334, 2025). "ChIP-qPCR confirmed that RUNX2 directly binds to Site1 and Site2 of the COL10A1 promoter, and multiplex immunofluorescence further showed co-localization of RUNX2 and COL10A1 in fibroblasts (Primary Tumor: n = 35), indicating direct transcriptional activation." (PMID 40826474, 2025). "Consequently, RUNX2 and HIF-1α synergistically promote angiogenesis, a vital process in the tumour microenvironment that provides nutrients and oxygen to the growing tumour." (PMID 40806771, 2025). "In addition, RT-qPCR analysis revealed that LOXL2 and SPTBN1 were predominantly expressed in normal cell lines, whereas higher levels of NCKAP1L, RUNX2, and WFS1 were detected in tumor cell lines." (PMID 41164190, 2025). "Importantly, RUNX2′s ability to stabilize HIF-1α and amplify angiogenesis in normoxic regions highlights its role in reshaping the bone niche to favour tumour colonization." (PMID 40806771, 2025). "Runx2 was highly expressed in cells and tissues of human esophageal carcinoma, and it also activated the PI3K/AKT and ERK signaling pathways, contributing to tumor growth and progression." (PMID 39595568, 2024). "The results revealed low expression of ALPL, RUNX2, and CLEC11A in PC, while highly expressed in PT and MLN (all p < 0.05, Wilcoxon test), which suggested abnormal activation and malignant transformation of OB cells during tumor progression." (PMID 38755647, 2024). "Finally, dendritic cell infiltration was detected in 24 tumor types for RUNX1, in 24 types for RUNX2, and in 26 types for RUNX3." (PMID 36321611, 2023). "RUNX2 might be directly repressed by the miR-455 molecule in human HCC samples, which has already demonstrated tumour-suppressive properties." (PMID 37759525, 2023). "The luciferase activity of these cells in the Runx2-expressed tumor cells gradually decreased with the increased expression of E-cadherin, indicating that E-cadherin inhibited MMP13 transactivation in a dose-dependent manner in the Runx2-expressed tumor cells." (PMID 37150786, 2023). "According to current knowledge, RUNX2 acts as an oncogene and is related to the more aggressive forms of the disease, whereas RUNX3 exerts a tumour-suppressive role and could be used as a biomarker for early HCC detection." (PMID 37759525, 2023). "The expression of P‐MAPK11 and RUNX2 protein was closely related to Fuhrman grade but not to such factors as age, gender, the stage and size of tumour." (PMID 37525479, 2023). "The results revealed that tumor tissue (LuCa) and the A549 cell line had higher RUNX2 expression levels than nontumor tissue (NT)." (PMID 36510562, 2022). "RUNX2 stabilizes HIF-1α protein for regulating optimal angiogenesis in chondrocytes, but overexpressed RUNX2 in cases of cancer increases VEGF expression and anti-apoptotic activity under hypoxia, resulting in increased tumor progression." (PMID 36231060, 2022).